PARP1 (poly(ADP-ribose) polymerase 1)
Diseases named in the same sentence as PARP1 in open-access papers (continued):
Sharing a sentence is not in itself a finding about the gene and the disease.
cancer (continued). "The improved PARP1 trapping activities of veliparib and olaparib by the L777P mutation has been shown to translate into significantly improved efficacy of both the PARPi in BRCA1m cancer cells." (PMID 41459749, 2025). "Therefore, to avoid cytotoxicity in HRR-proficient cells, PARP1 trapping should selectively occur in HRR-deficient cancer cells, as observed with saruparib." (PMID 41459749, 2025). "Furthermore, we found that HELLS is co-expressed with PARP1 in cancer cells, and its loss is synthetic lethal with homologous recombination deficiency (HRD)." (PMID 41297801, 2025). "Additionally, PARP1 knockout mice exhibit reduced tumor growth, particularly in pancreatic and colorectal cancers, underscoring the association between parthanatos and cancer progression." (PMID 40564403, 2025). "PARP-1 has been linked to the progression of several types of cancer." (PMID 39858519, 2025). "In addition to cancer, PARP-1 hyperactivity is implicated in the pathogenesis of many metabolic, cardiovascular, and neurodegenerative diseases and generally in inflammatory and aging-related diseases." (PMID 39941940, 2025). "However, in cancer cells with harboring mutation that able accumulate 5′dRP groups likely provide the opportunity of PARP1 to stay longer on the DNA substrate and causes genotoxicity." (PMID 41568291, 2025). "PARP1 remodels cancer-associated chromatin by PARylating the nucleosomal core histones and chromatin-bound regulatory factors, thereby promoting chromatin accessibility at promoters and supporting c-MYC- and E2F-driven proliferative gene expression in tumor contexts." (PMID 41460301, 2025). "PARG and NAMPT inhibitors could therefore represent therapeutic opportunities for cancers displaying PARP1 hyperactivity, including XRCC1-deficient cancers." (PMID 41459749, 2025). "To date, the frequency of PARP1 mutations that result in PARP1 hyperactivation within cancer populations remains unclear." (PMID 41459749, 2025). "Additionally, PARP1 is known to interact with the core circadian clock network, which regulates several cancer hallmark genes." (PMID 40382284, 2025). "Finally, both PARP-1 and iNOS have been implicated in the regulation of stemness in several types of cancer." (PMID 39858519, 2025). "Activation and/or upregulation of TRPM2, NOX2, and PARP-1 have been linked to many cancers." (PMID 40722879, 2025). "High PARP1 expression was associated with high nucleolar localization of DDX21 in both cancers." (PMID 38767454, 2024). "Furthermore, PSIP1 depletion sensitises cancer cells to clastogens that cause R-loop-induced DNA damage and PARP1 inhibitors." (PMID 38191578, 2024). "Additionally, the disruption of PARP1 in transcriptional regulation adds complexity, affecting oncogenes implicated in cancer cell survival." (PMID 39125873, 2024). "PARP1 inhibitors are successfully used for cancers deficient in HR due to BRCA mutations." (PMID 38191578, 2024). "On the opposite hand, NAD may actually prevent cancer, as it is a substrate for the DNA-repair enzyme PARP-1, which prevents cancer-promoting mutations." (PMID 39200120, 2024). "Notably, the potency of various clinical PARPis in trapping PARP1/2 correlates with their efficacy in killing BRCA1/2-deficient cancer cells, suggesting that PARPi induces DNA damage by trapping PARP1/2 on DNA." (PMID 39007266, 2024). "However, the dependence of BRCA1 deficient cancer cells on PARP1 S-phase activity predicts that loss of this activity such as by targeting FANCJ will be a therapeutic option." (PMID 38521768, 2024). "Additionally, PARP1 has been implicated in the pathogenesis of several carcinomas due to its overexpression in these malignancies." (PMID 39056736, 2024). "Owing to these aspects, PARP1 inhibitors have been used in combination with cancer-killing drugs that partially cause DNA damage as a target for drug development research, effectively improving the efficiency of drugs to kill cancer cells." (PMID 37060095, 2023).
cancer (continued). "Therefore, PARP1 is one of the most intensively investigated targets for treating cancers associated with BRCA1/2 deficiency." (PMID 36838818, 2023). "Cancer cells with homologous recombination (HR) deficiency are known to be exquisitely sensitive to poly[adenosine 5′-diphosphate (ADP)-ribose] polymerase 1 (PARP1) inhibitors (PARPi)." (PMID 37878693, 2023). "Overexpression of PARP1 is linked to poor survival overall in cancer." (PMID 36809279, 2023). "However, using PARP1 knockout cells, Hopkins and colleagues showed that PARP1 is the primary target in causing cytotoxicity in BRCA1/2 mutant cancers." (PMID 37035242, 2023). "In addition, we demonstrated that PARP-1 inhibition caused a strong accumulation of Ets-1 in cancer cells." (PMID 37686260, 2023). "As such, it is tempting to speculate that IDH1 mutant ALT cancers may exhibit high levels of trapped PARP1 through loss of XRCC1 protein activity." (PMID 36940725, 2023). "Aberrant PARP1 activity has been associated with the development and progression of cancer." (PMID 37415147, 2023). "The current review expands on PARP1’s potential importance as a new therapeutic target for clinical applications by expanding its numerous roles linked with DNA methylation in normal and cancer cells." (PMID 35327610, 2022). "It was shown that in HR-deficient cancers, including BRCA1- or BRCA2-deficient cancers, the inhibition of PARP1 could lead to the accumulation of unrepaired SSBs and their conversion into DSBs through replication fork collision." (PMID 36497058, 2022). "Together, an HRD mutation and PARP1 inhibition is lethal to cancer cells." (PMID 35453890, 2022). "PARP1 inhibitors have been shown to have notable efficacy in HR-deficient cancer cells." (PMID 35488020, 2022). "Besides catalytic inhibition of PARP protein, other important mechanism of PARPi involves trapping of PARP1 protein on the damaged site of DNA, causes blockade of replication and transcription fork and ultimately leads to death of cancer cells." (PMID 36094927, 2022). "The protein concentration of PARP-1 may be altered as a result, resulting in an increase in susceptibility to cancer." (PMID 36432602, 2022). "PARP1 is a promisingtreatment target in BRCA-deficient carcinomas." (PMID 35293552, 2022). "Moreover, in pRb-mutated cancer cells, where entry into S phase is unimpeded, PARPi or PARP1 knockdown sensitized cells to DNA-damaging chemotherapeutics; thus, caution should be used when treating pRb mutated cancers with PARPi therapy." (PMID 33922595, 2021). "In the so-called “BRCAness”, BRCA1/2 mutations are the biomarkers to predict cancer patients that could benefit from PARP1 inhibitors as a therapeutic strategy." (PMID 33671256, 2021). "In the clinics PARP1 inhibitors are successfully used to treat BRCA1 mutated cancers." (PMID 34395585, 2021). "Finally, we found that PARP1 alterations were markedly associated with MSI status in TCGA pan-cancer cohorts (P < 0.0001)." (PMID 34531868, 2021). "Since the BIN1 gene rarely mutates in human cancers, our results suggest that simultaneous inhibition of PARP1 and ATM provokes a new BRCAness-independent synthetic lethal effect and ultimately re-establishes cisplatin sensitivity even in platinum-refractory cancer cells." (PMID 34948122, 2021). "Inhibition of PARP-1 impairs DNA damage repair and causes apoptosis of cancer cells." (PMID 34384442, 2021). "Moreover, PAC has also been associated with BRCA1/2 mutations and there are ongoing early-phase studies using PARP1 inhibitors in this cancer." (PMID 33923200, 2021). "Moreover, the B,D-bilactam ASA-B and the B-lactam ASA-A steroid alkylators instigated higher increases of PARP1 mRNA cellular content in the UWB1.289 + BRCA1 than in BRCA1 mutated UWB1.289 cancer cells." (PMID 34440232, 2021). "PARP1 inhibitors are a clinically approved treatment for certain types of BRCA-deficient cancers." (PMID 34887904, 2021).
cancer (continued). "Inhibiting PARP1 is a promising strategy for cancers with HR deficiency." (PMID 34880209, 2021). "The idea is by blocking DNA repair pathways through PARP1 inhibitor in BRCA mutated cancers, the DNA damage responses will initiate signaling pathways to promote cell-cycle checkpoint activation, thus apoptosis will be triggered to eliminate cancer cells efficiently." (PMID 34207284, 2021). "The anti-cancer efficacy of Regorafenib was significantly reduced in 3D bioengineered cells when compared to 2D cultures and dose-dependently associated with cell apoptosis by cleaved PARP-1 activation and P-STAT3 inhibition." (PMID 34638417, 2021). "The seminal findings that inhibition of PARP1/2 in BRCA1/BRCA2 mutated cancer cells selectively kills the cancer cells, but leaves the wild type BRCA1/BRCA2 cells intact, helped define a new epoch in personalised medicine that is already transforming patients’ lives." (PMID 34950659, 2021). "Regular consumption of citrus fruit reduces the risk of cancer, and this effect is likely associated with inhibition of PARP-1 by flavonols naringenin (NG), hesperetin (GP) and their O-glycoside forms naringin and hesperidin, which are contained in citrus fruit." (PMID 34768872, 2021). "Our results were also consistent with the previous findings of two meta-analyses, which reported that the allele frequency of A in the PARP-1 V762A polymorphism is significantly higher in Asian patients compared to Caucasians and related to a higher risk of cancer development." (PMID 34830749, 2021). "Mechanistically, blocking PARP1’s enzymatic activity compromises the repair of SSBs, which become converted to double-stranded breaks (DSBs) during DNA replication, thus inducing synthetic lethality in cancer cells with deficient HR." (PMID 34681760, 2021). "PARP1 trapping causes excessive DNA Double-Strand Breaks (DSB) during the S-phase of the cell cycle by the collapse of stalled replication forks supporting cancer cell death." (PMID 34207240, 2021). "Synthetic lethality is a novel paradigm in cancer treatment regimens that combines a cancer-inherent genetic mutation (such as BRCA1 or BRCA2 mutation) with the pharmacological inhibition of a specific molecular target (such as PARP1)." (PMID 34572428, 2021). "Indeed, the initial designation of these compounds to BRCA1/BRCA2-mutated cancers already stemmed from the discovery of the synthetic lethal relationship between PARP1/PARP2 inhibition and faulty HR machinery." (PMID 34210965, 2021). "Therefore, inhibition of PARP1 can effectively inhibit the growth of cancer cells with HR deficiency." (PMID 34880209, 2021). "All these studies suggest that EGF can regulate PARP1, which might impact the efficacy of cancer therapy, particularly when DNA damage is caused by cancer therapy." (PMID 32093123, 2020). "In conclusion, our meta‐analysis showed that PARP‐1 gene rs1136410 C>T polymorphism may contribute to increased cancer risk among Asian populations." (PMID 33108038, 2020). "Since PARP1 is a promising target for precision therapy by selectively treating DNA repair-deficient cancers, the detailed examination of the underlying molecular processes of PARP1-dependent PARylation can give us a starting point to improve our methodologies and develop future therapies." (PMID 32358582, 2020). "Maybe, the discrepant role of PARP1 in cancer susceptibility or prognosis of cancer patients might be explained partly by PARP1’s involvement in various molecular and cellular processes." (PMID 33112558, 2020). "Some of these alterations could compromise XRN2 function and might render these cancers susceptible to PARP1 inhibition." (PMID 32859985, 2020). "The current study indicated that PARP1 rs1136410 C>T polymorphism may have an impact on certain types of cancer susceptibility." (PMID 33108038, 2020). "PARP‐1 rs1136410 T>C genetic polymorphism was previously investigated in various types of cancer." (PMID 33108038, 2020).
cancer (continued). "Further analysis of the mechanisms in nutlin-3a-induced PARP1 degradation may lead to the development of novel PARP1 suppressors applicable for cancers with BRCA1 mutation." (PMID 32405340, 2020). "Therefore, new strategies in cancer therapy seek to inhibit PARP activity because knock-out mice for PARP-1 and -2 showed profound deficiencies in the mechanisms of DNA repair, as well as greater sensitivity to ionizing radiation or alkylating agents." (PMID 33276556, 2020). "Finally, combining functional and genetic information retrieved by several databases, we selected genes that are correlated to cancer development and also linked to PARP1." (PMID 31105872, 2019). "Germline mutations of PARP1 oncogene are implicated in several types of cancer." (PMID 31413734, 2019). "PARP1 gene played an important role in DNA repair and cell apoptosis, the cell with PARP1 deficiency show resistance to DNA damage-induced programmed cell death and increased cancer risk." (PMID 32038722, 2019). "Indeed, it has been showed that the synthetic lethality approach using PARP-1 inhibition is maximum in BRCA1/2 deficient cancer patients." (PMID 31717700, 2019). "PARP1 activated in this way enables activation of specific transcription factors that promote the expression of ‘immediate early genes’ implicated in long term memory acquisition, development of heart muscle and transformation into cancer cells." (PMID 30993015, 2019). "Inhibition of PARP1 in BRCA-mutated cancers has been observed to be clinically beneficial." (PMID 30551210, 2019). "Inhibition of PARP1 activity in homologous recombination deficient cancer cells causes accumulation of unrepaired single-strand DNA breaks which are potentially converted to double-stranded DNA breaks, causing cell death selectively in those cancer cells." (PMID 30551210, 2019). "In Caucasian populations, the PARP1 Val762Ala gene variant minimizes the risk of development of some cancers, while in Chinese populations PARP1 762Ala gene variant increases the risk of cancer in numerous studies." (PMID 30183716, 2018). "Overall, these findings increase our understanding of how PARP1 may suppress deleterious phenotypes associated to aging, inflammation and cancer in humans." (PMID 29590171, 2018). "In addition, there was a direct association between PARP1 and the key cancer gene of NSCLC: EGFR, ALK in the interaction network of genes." (PMID 29152079, 2017). "In this study, to investigate the functional relationship between the HR factor Rad54 and Parp-1 in development and oncogenesis in vivo, we introduced single or combined Rad54 and Parp-1 inactivating mutations in a well characterized cancer model, the Ptc1 heterozygous mice." (PMID 29254138, 2017). "Our results show that an inhibitor of PARP1 (Olaparib) sensitizes NEIL3 deficient cancer cells." (PMID 29348879, 2017). "Approval of the PARP1/2 inhibitor AZD2281 (also known as olaparib) for the treatment of BRCA-deficient ovarian cancer in 2014 marked the successful establishment of such a therapeutic strategy for cancer in the clinic." (PMID 27926532, 2017).
cancer (continued). "Initial studies report that PARP1 is a promising target for treatment of BRCA-deficient carcinomas." (PMID 28991194, 2017). "PARP1 inhibitors can not only reduce inflammation-related side effects caused by chemotherapy and surgery injury, but also be used as potential preventative and antitumoral agents against carcinomas." (PMID 28991194, 2017). "Previous studies reported that defects in PARP-1 are enhancing cancer risk." (PMID 27746584, 2016). "As a result, PARP-1/2 inhibition by ABT-888 would be more effective at sensitizing cells to single-strand DNA breaks if patients have BRCA- or homologous recombination-deficient cancer." (PMID 26449224, 2015). "Here we demonstrate that miR-124 directly targets the mRNAs encoding both ATMIN and PARP1, suggesting that miR-124 may constitute a target or potential therapeutic in cancer treatment." (PMID 26115122, 2015). "PARP-1 regulates the activation of both transcription factors, and PARP inhibition or PARP-1 deficiency reduces the transcriptional activity of NF-κB and/or AP-1 in models of septic shock, inflammation, and ischemic-reperfusion, as well as in cancer and RA." (PMID 26339143, 2015). "Therefore, PARP1 is thought of as one of therapeutic targets for the development of anti-cancer treatments particularly for BRCA-mutated tumors, and a variety of clinical trials are actively in progress." (PMID 26540566, 2015). "In addition, our study shows that POLB polymorphism perturbs the BER pathway and sensitizes cancer cells to PARP1 inhibitors." (PMID 26090616, 2015). "Hence, we performed the present updated meta-analysis with addition of newly published studies on such association to further elucidate the role of the PARP1 Val762Ala polymorphism in cancer susceptibility." (PMID 24489833, 2014). "However, the rationale for the use of targeted agents such as PARP1 inhibitors (PARP1i) in BRCA2‐deficient cancers is contingent upon bi‐allelic BRCA2 inactivation in the tumour cells." (PMID 24268522, 2014). "This could suggest that higher expression of PARP-1 could predispose to further development of cancer." (PMID 25526641, 2014). "Our findings suggested that the PARP-1 Val762Ala polymorphism may function in cancer development in an ethnicity- or cancer-specific manner." (PMID 24853559, 2014). "The discrepancy in the MAF of PARP1 Val762Ala polymorphism between ethnicity may slightly shed light on the observation that this polymorphism differentially modulates cancer susceptibility between Asians and Caucasians." (PMID 24489833, 2014). "Meta-analysis of the association between PARP1 Val762Ala polymorphism and cancer risk." (PMID 24489833, 2014). "Further studies may focus on the influence of gene-gene and gene-environment interactions on the association of cancer and PARP-1 Val762Ala polymorphism." (PMID 24853559, 2014). "It remains unclear whether the PARP1 Val762Ala polymorphism affects cancer risk through the same biological mechanism across different types of cancer or ethnic group." (PMID 24489833, 2014). "Moreover, PARP1 expression and activity varies greatly in human tumors, and SNPs in PARP1 have been associated with numerous cancers." (PMID 23593019, 2013). "PARP-1 Val762Ala was well-known to be associated with increased risk of several cancers." (PMID 24392019, 2013). "This may be due to apoptotic pathway deficiencies in these cancer cells, in which the DNA damage response pathways may be activated by transiently activating PARP1 to induce necrotic cell death." (PMID 23433042, 2013). "Thus, PARP-1-mediated PARylation is involved in a specific regulation of Ets-1 protein levels in cancer cells and we assume that this mechanism is linked to its proteasomal degradation." (PMID 23405229, 2013). "Variant forms of PARP-1 with decreased catalytic activity, such as those created by small nucleotide polymorphism (SNP), could make cancer cells resistant to PARPi." (PMID 23450678, 2013).